SPARC (secreted protein acidic and cysteine rich)
Diseases named in the same sentence as SPARC in open-access papers (continued):
Sharing a sentence is not in itself a finding about the gene and the disease.
Alzheimer disease (4 papers, 2023 to 2025). A progressive, neurodegenerative disease characterized by loss of function and death of nerve cells in several areas of the brain leading to loss of cognitive function such as memory and language. "SPARC has demonstrated high expression in the brains of patients with Alzheimer’s disease, where it binds to Aβ protein deposits, actively contributing to neuroinflammation and subsequent tissue repair." (PMID 41009953, 2025). "Distinct immune markers were found to differentiate FTD from Alzheimer’s disease (AD) and amyotrophic lateral sclerosis (ALS), with GFAP, SPARC, and SPP1 varying between FTD and AD and IL-15, HERV-K, NOD2, and CHIT1 differing between FTD and ALS." (PMID 40305176, 2025).
astrocytoma (4 papers, 2012 to 2025). "Comparison of the grade 3 astrocytoma to the matched normal sample, revealed the top three DEGs encoding ECM glycoproteins (NTN1, AEBP1 and SPARC) and ECM-affiliated factors (C1QA, LGALS9 and C1QL1)." (PMID 41366031, 2025). "A subsequent study showed SPARC to have restricted expression to the marginal glia of the outer layer of the cortex, Bergmann glia in the cerebellum, and an unidentified subpopulation of cells in the subcortical white matter, and to be highly expressed in all grades of astrocytomas." (PMID 22480225, 2012). "We previously demonstrated that SPARC protein is not immunohistochemically detectable in normal human cerebral cortex but is highly expressed in human astrocytomas grades II-IV." (PMID 22480225, 2012).
cataract (4 papers, 2011 to 2025). Partial or complete opacity of the crystalline lens of one or both eyes that decreases visual acuity and eventually results in blindness. "ITGB1 and SPARC exhibit lens epithelial cell-like characteristics in cataracts." (PMID 35721704, 2022).
cyst (4 papers, 2006 to 2024). A sac-like closed membranous structure that may be empty or contain fluid or amorphous material. "Another gene identified in this study, SPARC, known to be upregulated in angiogenesis, may be associated with angiogenesis around the cyst." (PMID 31240209, 2019). "In addition, in vitro experiments have used SPARC to analyze cyst-lining epithelial cells (CLECs)." (PMID 23516489, 2013).
diabetic nephropathy (4 papers, 2020 to 2025). "In vivo, streptozotocin-induced diabetic nephropathy was less severe in SPARC-null compared to wild type mice, again demonstrating an active role for SPARC in driving kidney dysfunction." (PMID 37371758, 2023). "SPARC -/- mice have decreased laminin and collagen IV deposition in renal tissue, decreasing damage from experimental diabetic nephropathy." (PMID 33147244, 2020). "Nephroseq v5 webserver predicted the over expression of FN1, SPARC, LUM, VCAN, and POSTN with fold change of 2.808, 1.655, 6.25, 1.77, and 3.324 in diabetic nephropathy respectively." (PMID 34557161, 2021).
endothelial dysfunction (4 papers, 2021 to 2025). In vascular diseases, endothelial dysfunction is a systemic pathological state of the endothelium (the inner lining of blood vessels) and can be broadly defined as an imbalance between vasodilating and vasoconstricting substances produced by (or acting on) the endothelium. "miR-484 might influence SOX7 expression or activity, and SOX7 might influence the SPARC expression or activity, thereby affecting the downstream pathways involved in endothelial dysfunction and VC." (PMID 39596822, 2024). "Second, the current study did not clarify the precise mechanisms by which SPARC and ADAMTS1 contribute to vascular inflammation and endothelial dysfunction." (PMID 40362650, 2025).
esophageal adenocarcinoma (4 papers, 2003 to 2025). A malignant tumor with glandular differentiation arising predominantly from Barrett mucosa in the lower third of the esophagus. "Knockdown of TGFBR2 impairs TGF-β signaling induced by SPARC in esophageal adenocarcinoma cells." (PMID 37569556, 2023).
Hyperglycemia (4 papers, 2019 to 2025). An increased concentration of glucose in the blood. "Therefore, the study on the functions of SPARC may reduce the damage caused by ischemia, hypoxia, hyperglycemia, and hyperlipidemia to brain tissue in order to promote novel research on the occurrence and development of neurological diseases." (PMID 33584170, 2020). "In diabetic canine and mouse models, SPARC significantly reduced hyperglycemia, improved glucose tolerance, and markedly increased both pancreatic islet area and insulin secretion." (PMID 41185072, 2025). "Compared to the DM group, treatment with SPARC-MSCs resulted in significant improvements in hyperglycemia, body weight, and OGTT outcomes in the diabetic mice." (PMID 41185072, 2025). "We found that in vivo administration of SPARC significantly ameliorated hyperglycemia, gradually restored STZ-induced islet damage, and facilitated the recovery of β-cells function and insulin production." (PMID 41185072, 2025).
mesothelioma (4 papers, 2022 to 2023). A usually malignant and aggressive neoplasm of the mesothelium which is often associated with exposure to asbestos. "SPARC gene overexpression has shown to be associated with poor survival in the mesothelioma (MESO) cohort from the TCGA database, indicating that this gene may be a powerful prognostic factor in MESO." (PMID 37509139, 2023). "Furthermore, it might be of interest to investigate the contribution of RNA editing in the increased expression of COL5A2, ITGAV, and SPARC genes, which is correlated with mesenchymal phenotype in mesothelioma." (PMID 36769192, 2023). "The top four genes (COL5A2, ITGAV, SPARC, and ACTA2) associated with the strongest correlation with EMT Top50 mesenchymal genes were selected for further analysis, confirming their prognostic importance in mesothelioma and other solid tumors using the TCGA database of online platforms." (PMID 36901697, 2023). "However, it remains unknown whether the SPARC gene is a promoter of mesothelioma cell stemness." (PMID 37509139, 2023). "Fluorescent immunostaining of human mesothelioma cell lines showed that sarcomatoid CRL-5946 cells expressed COL5A2 and SPARC dramatically higher compared to epithelioid CRL-5915 cells, while CRL-5915 cells expressed epithelial marker EpCAM specifically." (PMID 35046456, 2022). "Besides a few sporadic studies, this may be the first study to identify COL5A2, ITGAV SPARC and ACTA2 as a panel of emerging EMT genes in mesothelioma." (PMID 35046456, 2022).
metastatic cancer (4 papers, 2014 to 2022). A carcinoma which has spread from the original site of growth to another anatomic site. "In this regard, SPARC (secreted protein acidic and cysteine-rich) has already been reported in different types of metastatic cancer—including CRC—and has attracted attention as a possible biomarker." (PMID 34439343, 2021). "The diverse functions of SPARC, compounded by the challenge of studying cell invasion and BM dynamics in vivo, have made it difficult to understand how overexpression of SPARC in metastatic cancers promotes cell invasion and tumor spread." (PMID 26926673, 2016). "SPARC is an extracellular matrix protein that is present at high levels in many metastatic cancers where it promotes tumor invasion into neighboring tissues." (PMID 26926673, 2016). "There are five genes (BGN, THBS2, SPARC, CDH11 and SPP1) in metastatic cancer tissues that are significantly higher than non‐metastatic cancer tissue at the transcriptomics level, while only BGN and THBS2 were significant difference in protein expression between metastatic and non‐metastatic cases." (PMID 36377223, 2022). "Whether SPARC overexpression promotes invasive ability in the AC, similar to its effect on tumor cells in metastatic cancer, is not known." (PMID 26926673, 2016). "There is evidence for differential postranslational processing of SPARC in different cell types, potentially leading to differential functions, and it remains to be explored if this applies to non-neoplastic vs. neoplastic or non-metastatic vs. metastatic cancer cells." (PMID 25331979, 2014).
metastatic melanoma (4 papers, 2009 to 2022). A melanoma that has spread from its primary site to another anatomic site. "In freshly isolated metastatic melanoma cells, a positive association between SPARC and SLUG mRNA levels was also found." (PMID 22911700, 2012). "Primary and metastatic melanoma samples expressed high levels of SPARC in malignant cells and in intermingled fibroblasts and endothelial cells, whereas dysplastic nevi, benign nevi and normal melanocytes exhibited low to none SPARC expression." (PMID 19337591, 2009). "For example, a high expression of SPARC has been reported in advanced, metastatic melanoma." (PMID 36430810, 2022). "SPARC has also been shown to be strongly expressed in advanced primary and metastatic melanomas." (PMID 28974924, 2018).
ovarian tumor (4 papers, 2009 to 2019). "To further confirm the role of adipocyte-SPARC on ovarian tumour growth in vivo, we injected ID8 cells with SP+/+ and SP–/– omental adipocytes (1:2, cancer cell:adipocyte ratio) subcutaneously in 6-week-old female athymic nude mice." (PMID 30765860, 2019). "This is supported by data from ovarian tumor samples illustrating cancer cells lack SPARC mRNA, but do contain SPARC protein as assessed by immunohistochemistry." (PMID 27622658, 2016). "This is again supported by recent evidence illustrating that in SPARC null mice ovarian tumors are more responsive to cisplatin therapy." (PMID 27622658, 2016). "Moreover, elevated SPARC expression has been shown to occur in the activated stroma surrounding ovarian tumors, leading to the suggestion that it may be modulating the ovarian tumor microenvironment through regulation of matrix metalloproteinases, inflammation, and pro-migratory cytokines." (PMID 27622658, 2016).
pterygium (4 papers, 2009 to 2023). A wedge-shaped fibrovascular lesion arising from the bulbar conjunctiva and extending to the cornea. "Knockdown of SPARC attenuates the fibrotic effect induced by TGF-β1 at least in part, by inactivating the SMAD2/3 pathway in human pterygium fibroblasts." (PMID 37569556, 2023). "Genes up-regulated in pterygium include fibronectin (FN1), CEACAM5 (CEA), CD24, SPARC, MSMB and TFF1." (PMID 19272163, 2009). "Interestingly, a recently published study demonstrated that silencing of SPARC inhibited the expression of profibrotic markers, such as alpha smooth muscle actin and FN1 in human pterygium fibroblasts and also mitigated their migration and contractile phenotype." (PMID 35174178, 2021). "Other up-regulated proteins like small proline rich protein 1B (SPRR1B), CD24, S100 calcium binding protein, SPARC, TFF1, SPRR1B and SERPINB13 also govern the wound healing process and cornification of epithelium, again, supporting the hypothesis of aberrant wound response in pterygium." (PMID 19272163, 2009).
squamous cell carcinoma (4 papers, 2010 to 2017). A carcinoma arising from squamous epithelial cells. "Both SPARC in squamous cell carcinoma of the oral cavity and tumor-associated stromal cells are associated with poor prognostic factors, such as daily smoking." (PMID 28718842, 2017). "SPARC-null mice were recently demonstrated to resist UV-induced squamous cell carcinoma, suggesting a tumor-promoting role of SPARC." (PMID 20096135, 2010). "In addition, higher SPARC expression used to be found in squamous cell carcinoma." (PMID 29152093, 2017).
Stroke (4 papers, 2018 to 2021). Sudden impairment of blood flow to a part of the brain due to occlusion or rupture of an artery to the brain. "We performed this analysis in our companion paper, where SPARC was seen to be responsive to change over time in the early phase post stroke and longitudinally associated with clinical measures of motor impairment within subjects." (PMID 34702281, 2021). "How the increased muscle synergies during reaching after stroke are longitudinally associated with SPARC within subjects remains to be investigated." (PMID 34560898, 2021). "Despite the likely similar time courses of SPARC and FM-UE, and longitudinal within-subject association, the underlying neurophysiological cause of diminished smoothness after stroke remains unclear and requires further investigation." (PMID 34560898, 2021). "The significant longitudinal association between SPARC and FM-UE within subjects and their similar time window of recovery of 5 weeks post stroke suggest that their recovery may be driven by a common underlying process responsible for spontaneous neurological recovery early post stroke." (PMID 34560898, 2021). "The effect of time after stroke was significant for weeks 1 to 4 after stroke for SPARC and FM-UE (P < 0.05)." (PMID 34560898, 2021). "SPARC showed a gradual increase over time towards the reference values of the healthy individuals; it levelled off in week 5, yet remained lower in the patients who suffered a stroke than the age-matched healthy individuals (P < 0.05/Ns)." (PMID 34560898, 2021). "Correlations between clinical parameters and SPARC values in the stroke and control groups." (PMID 33886640, 2021).
cardiac hypertrophy (3 papers, 2021 to 2023). "The expression of SPARC is markedly increased in the experimental models of cardiac hypertrophy and fibrosis." (PMID 34926700, 2021). "Thrombospondins (TSP), tenascins, Cilp-1, secreted protein acidic and rich in cysteine (SPARC), osteopontin and members of the CCN family are involved in a variety of cardiac pathophysiologic conditions such as MI, cardiac hypertrophy, aging, diabetic cardiomyopathy and valvular disease." (PMID 37358728, 2023).
cardiomyopathy (3 papers, 2021 to 2023). A disease of the heart muscle or myocardium proper. "Several studies evaluated SPARC in the heart and showed that SPARC-null or SPARC-deficient animals had blunted age-related changes to collagen and cardiac stiffness, whereas overexpression leads to a cardiomyopathy phenotype." (PMID 34827715, 2021). "This cardiomyopathy phenotype is a result of elevated Secreted Protein Acidic and Rich in Cysteine (SPARC) levels, a matricellular protein, which is involved in mammalian cardiac function, in the absence of nephrocytes." (PMID 37171583, 2023).
colitis (3 papers, 2013 to 2025). Inflammation of the colon. "We observed that SPARC was highly expressed in CD patients and animal models of experimental colitis and was positively associated with the disease progression." (PMID 39888301, 2025). "Together, USP22 deficiency induced the upregulation of SPARC via affecting H3K27ac and H2Bub1 occupancy in human CRC cells and elevated SPARC levels in the colons of mice experiencing colitis and inflammation-associated CRC." (PMID 33920268, 2021). "Furthermore, mice deficient in SPARC exhibits resistance to chemically induced colitis, a phenomenon associated with the modulation of barrier‐associated proteins." (PMID 39888301, 2025). "Our study revealed a significant increase in SPARC expression in the colonic mucosa of both CD patients and colitis mice." (PMID 39888301, 2025). "In conclusion, our findings revealed that SPARC, increased in CD patients and colitis mice, resulted in intestinal barrier damage by directly interacting with OTUD4, and activating the MYD88/NF‐κB/MLCK/MLC2 pathway." (PMID 39888301, 2025). "The results showed a significant reduction in DAO and D‐LA in SPARC KO mice during colitis compared with WT mice." (PMID 39888301, 2025). "This study demonstrates that SPARC is significantly overexpressed in both CD patients and murine models of colitis." (PMID 39888301, 2025). "Overall, these data indicate that SPARC influences intestinal epithelial barrier and colitis progression by modulating MYD88/NF‐κB signaling." (PMID 39888301, 2025). "Then, we next sought to explore how the SPARC/OTUD4 axis regulated the intestinal epithelial barrier during colitis." (PMID 39888301, 2025). "Together, our findings uncover that USP22 controls SPARC expression and inflammation intensity in colitis and CRC." (PMID 33920268, 2021). "In a later study, Sparc null mice were treated with 3% DSS for seven consecutive days to evaluate the role of SPARC in colitis." (PMID 33920268, 2021). "The clinical parameters of colitis were all noticeably less in the SPARC KO mice and these were accompanied by significantly lower micro-endoscopic inflammatory scores." (PMID 24204877, 2013). "As the DSS-induced colitis model exhibits inflammatory and histopathological features that are similar to human colitis, it can be used as a model to assess the effect of the presence of SPARC and its role in the colonic inflammation of IBD." (PMID 24204877, 2013). "The data presented, however, demonstrated a potential pro-inflammatory role for SPARC in the DSS-induced model of murine colitis." (PMID 24204877, 2013). "These enriched pathways were closely associated with an intestinal barrier, hinting that SPARC KO may contribute to maintaining intestinal barrier function in colitis." (PMID 39888301, 2025). "Furthermore, SPARC depletion reduced intestinal barrier damage and colitis in the mouse model, colonic organoids, and cell lines." (PMID 39888301, 2025). "Notably, the SPARC expression was also modulated at the transcriptional level in colitis." (PMID 39888301, 2025). "Using a transcriptome-wide approach, we identified SPARC as the most highly upregulated gene following USP22 depletion and confirmed these findings in Usp22fl/fl mice experiencing acute colitis and CRC." (PMID 33920268, 2021). "SPARC KO and wild type (WT) mice received DSS to induce an acute colitis and were assessed over time for tissue reconstitution." (PMID 24204877, 2013). "Besides, the direct interaction between SPARC and OTUD4 was evidenced in the colonic tissues of DSS‐induced colitis mice." (PMID 39888301, 2025). "Interestingly, these results mechanistically connect USP22-mediated repression of SPARC expression via H2Bub1 deubiquitination, thereby possibly preventing the pro-inflammatory effect of SPARC in DSS-mediated colitis in mice." (PMID 33920268, 2021).
ductal breast carcinoma (3 papers, 2015 to 2023). "Our principal finding useful for a molecular classification was the very high expression of SPARC (70% incidence, as bone metastasis) in dysplastic epithelium, associated with ductal breast carcinoma, and in bone metastatic cells and stroma (ECM and supportive cells)." (PMID 26703564, 2015). "SPARC plasma levels in ductal carcinoma (DC) and in bone metastasis (ME)-bearing patients doubled and tripled, respectively, compared to that of normal women (CTR)." (PMID 26703564, 2015). "Similarly, we found that ductal carcinoma tended to be more frequent in patients with SPARC+ CAFs, and that patients with TNBC with SPARC+ CAFs were often younger." (PMID 36346290, 2023). "In this context, the present paper deals with the evaluation of SPARC expression during ductal breast carcinoma progression, from the dysplastic lesion until bone metastasis establishment: SPARC distribution in neoplastic cells versus stroma, and the plasma levels were examined." (PMID 26703564, 2015).
intervertebral disc degeneration (3 papers, 2011 to 2022). "It has been demonstrated that SPARC-null mice are affected by intervertebral disc degeneration and that they are nonresponders to bone-anabolic parathyroid treatment." (PMID 34638677, 2021).
invasive breast carcinoma (3 papers, 2015 to 2024). A carcinoma that infiltrates the breast parenchyma. "While normal mammary tissue has undetectable or lightly detectable amounts of SPARC, and benign breast lesions are weakly positive, 75% of both in situ and invasive breast carcinomas are strongly positive for SPARC in stromal cells (CD-34-negative, α-SMA-positive)." (PMID 26703564, 2015).